PKD1 (polycystin 1, transient receptor potential channel interacting)
Diseases named in the same sentence as PKD1 in open-access papers (continued):
Sharing a sentence is not in itself a finding about the gene and the disease.
autosomal dominant polycystic kidney disease (continued). "A TSC2/PKD1 contiguous gene syndrome, which is caused by a chromosomal mutation that disrupts both the TSC2 and PKD1 genes, has been identified in patients with tuberous sclerosis complex and severe early-onset autosomal dominant polycystic kidney disease." (PMID 31870441, 2019). "Autosomal dominant polycystic kidney disease (ADPKD) is an inherited monogenic renal disease characterised by the accumulation of clusters of fluid-filled cysts in the kidneys and is caused by mutations in PKD1 or PKD2 genes." (PMID 30858458, 2019). "Most ADPKD are genetically heterogeneous, with the following two identified causative genes: polycystic kidney disease 1 (PKD1) (OMIM 601313; 16p13.3), responsible for 85% of patients, and polycystic kidney disease 2 (PKD2) (OMIM 173910; 4q22.1), responsible for 15% of patients." (PMID 30424739, 2018). "These two transmembrane proteins are encoded by PKD1 or PKD2 genes, which are mutated in autosomal-dominant polycystic kidney disease (ADPKD), a genetic disorder characterized by uncontrolled proliferation of renal cells with the consequent formation of cysts and loss of renal function." (PMID 28353628, 2017). "For example, PKD1 and PKD2 form complexes that are thought to sense urine flow and elicit downstream Ca2+ signals in the kidney; defects in this process may underlie autosomal dominant polycystic kidney disease (ADPKD)." (PMID 27272319, 2016). "For this reason, we also included in our group of patients a girl from a family with clinically diagnosed autosomal dominant polycystic kidney disease (ADPKD), where linkage analysis of 8 family members (of which 7 were affected) showed that the disease was linked to the PKD1 gene." (PMID 26695994, 2015). "PKD1 and PKD2 mutations cause autosomal dominant polycystic kidney disease (ADPKD), often leading to kidney failure." (PMID 40909272, 2025). "Autosomal dominant polycystic kidney disease (ADPKD), a prevalent and potentially lethal monogenic disorder, is characterized by progressive renal cyst formation driven by mutations in PKD1 or PKD2, encoding polycystin-1 (PC1) and polycystin-2 (PC2), respectively." (PMID 41086943, 2025). "The human PKD1 gene locus is responsible for most cases of autosomal dominant polycystic kidney disease (ADPKD)." (PMID 41166294, 2025). "The identification of mutations in the PKD1 or PKD2 genes holds significant prognostic value, particularly in families with no known history of Autosomal Dominant Polycystic Kidney Disease (ADPKD)." (PMID 39457385, 2024). "In autosomal dominant polycystic kidney disease (ADPKD), pancreatic cysts are a marker of being 5.9 times more likely to have the PKD2 instead of the PKD1 mutation." (PMID 39058059, 2024). "Mutations of the polycystic kidney disease type 1 (PKD1) gene, which lies adjacent to TSC2 on chromosome 16p13.3, are responsible for autosomal dominant polycystic kidney disease (ADPKD)." (PMID 39323690, 2024). "Autosomal dominant polycystic kidney disease (ADPKD) is caused by mutations of the PKD1 or PKD2 genes, which encode the proteins polycystin-1 (PC1) and polycystin-2 (PC2), respectively." (PMID 36406261, 2022). "Autosomal dominant polycystic kidney disease (ADPKD) is the most common form of PKD, which is caused by mutations in either PKD1 or PKD2 genes that encode polycystin-1 (PC1) and polycystin-2 (PC2), respectively." (PMID 35159293, 2022). "Autosomal dominant polycystic kidney disease (ADPKD) is an inherited kidney disease caused by mutations in genes PKD1 and PKD2 encoding for proteins polycystin-1 (PC-1) and polycystin-2 (PC-2)." (PMID 36712680, 2022). "Autosomal dominant polycystic kidney disease (ADPKD) is the most common genetic disorder of the kidney, caused by mutations in the PKD1 and PKD2 genes that encode for transmembrane proteins polycystin-1 (PC1) and polycystin-2 (PC2), respectively." (PMID 35847973, 2022).
autosomal dominant polycystic kidney disease (continued). "Mutations in pkd1 or pkd2, which encode PC1 and PC2 respectively, result in autosomal dominant polycystic kidney disease (ADPKD), which is one of the most common cilia-related pathologies." (PMID 33919210, 2021). "The TSC2 gene lies immediately adjacent to PKD1 (OMIM #601313), which encodes polycystin-1 and is the major gene causing autosomal dominant polycystic kidney disease (ADPKD, MIM#173900)." (PMID 32695431, 2020). "Mutations in the polycystin genes, PKD1 or PKD2, result in Autosomal Dominant Polycystic Kidney Disease (ADPKD)." (PMID 30769894, 2019). "Mutations in the polycystin genes Pkd1 (encoding polycystin-1; PC1) and Pkd2 (encoding PC2) cause autosomal dominant polycystic kidney disease (ADPKD), the most common monogenic disease." (PMID 31048699, 2019). "Some SNP variants occurred at genes linked to other renal diseases including autosomal dominant polycystic kidney disease (ADPKD) (Pkd1) and autosomal recessive polycystic kidney disease (ARPKD) (Pkhd1) and cystic fibrosis (Slc9A3R2)." (PMID 30606755, 2019). "A recent analysis of mutations in the PKD1 or PKD2 genes leads to ~87% and 13%, respectively, of the cases of autosomal dominant polycystic kidney disease (ADPKD)." (PMID 31207979, 2019). "Mutations in the polycystin genes, PKD1 or PKD2, results in Autosomal Dominant Polycystic Kidney Disease (ADPKD)." (PMID 29443690, 2018). "Autosomal dominant polycystic kidney disease (ADPKD) is an incurable inherited chronic disorder characterized by progressive kidney enlargement and frequent end-stage renal disease due to numerous fluid-filled cysts that are induced by mutations and loss of heterozygosity in PKD1 or PKD2 genes." (PMID 29995892, 2018). "These calcium channels are formed by a complex of polycystin 1 and polycystin 2 (PC1 and PC2), encoded by the PKD1 and PKD2 genes, respectively, which cause autosomal dominant polycystic kidney disease (ADPKD) when mutated." (PMID 17357787, 2007). "The coexistence of tuberous sclerosis complex and autosomal dominant polycystic kidney disease due to a contiguous gene deletioninvolving TSC2 and PKD1 represents a rare but significant genetic syndrome." (PMID 40822828, 2025). "Renal ciliopathies are also associated with cystic kidney disease phenotypes, highlighted by autosomal dominant polycystic kidney disease (ADPKD), associated with pathological variants in polycystin-1 (PC1, encoded by PKD1) and polycystin-2 (PC2, encoded by PKD2)." (PMID 41140281, 2025). "Germline mutations in PKD1 and PKD2 genes cause autosomal dominant polycystic kidney disease (ADPKD), characterized by the enlargement of renal tubules and the formation of isolated fluid-filled cysts within the kidney and other organs such as the liver and pancreas." (PMID 39900437, 2025). "Mutations in PKD1 and PKD2 cause autosomal dominant polycystic kidney disease (ADPKD), a progressive inherited disorder in which the renal tissue is gradually replaced with fluid-filled cysts, giving rise to chronic kidney disease (CKD) and progressive loss of renal function." (PMID 37510333, 2023). "In addition, we discovered that loss of the Pkd1 gene product, polycystin-1 (PC1), whose mutation causes human autosomal dominant polycystic kidney disease (ADPKD), downregulates Bicc1 expression in vitro and in vivo." (PMID 24594709, 2014). "Major genes for TSC and autosomal dominant polycystic kidney disease (PKD), TSC2 and PKD1, respectively, lie adjacent to each other at chromosome 16p3.3, suggesting a role for PKD1 in the etiology of renal cystic disease in TSC." (PMID 19506736, 2008). "Genetic testing of PKD1 and PKD2 is expected to play an increasingly important role in determining allelic influences in autosomal dominant polycystic kidney disease (ADPKD) in the near future." (PMID 27835667, 2016).
autosomal dominant polycystic kidney disease (continued). "Autosomal dominant polycystic kidney disease (ADPKD; OMIM *601313 for PKD1, and *173910 for PKD2) is the most common hereditary kidney disease, predominantly characterized by the presence of cysts in both kidneys leading to end-stage renal disease (ESRD), usually in adulthood." (PMID 29973168, 2018).
cyst (232 papers, 2008 to 2026). A sac-like closed membranous structure that may be empty or contain fluid or amorphous material. "PKD1 truncating variants are associated with earlier onset of kidney failure and more rapid cyst expansion, whereas non truncating PKD1 variants and PKD2 mutations generally follow a slower course." (PMID 41597516, 2026). "In our lab, two macrophage phenotypes were identified in rapid-onset ADPKD mice, and we confirmed that macrophage-CLEC interactions promoted cyst growth in Pkd1-deficient mice." (PMID 41431718, 2026). "Apical ATP release is elevated in PKD1-deficient cyst-forming cells following pharmacological induction of HIF-1α and attenuated by two Pannexin-1 inhibitors, Probenecid and Brilliant Blue FCF (BB-FCF)." (PMID 42117913, 2026). "PKD1 truncating mutations are associated with earlier onset of kidney failure, faster cyst expansion, and higher total kidney volume, whereas PKD2 variants generally produce a milder disease course with slower progression." (PMID 41597516, 2026). "DNA methylation is known to silence gene expression and has been implicated in the downregulation of key cyst-suppressing genes, such as PKD1 and PKD2, which are essential for maintaining renal tubular cell integrity." (PMID 40801635, 2025). "By tracking cyst growth, researchers can correlate cyst characteristics with specific genetic mutations (e.g., PKD1 or PKD2) to better understand the disease’s underlying mechanisms, thereby facilitating the study of genotype–phenotype correlations." (PMID 41303287, 2025). "Due to the loss of PKD1/2 genes, cyst development can be initiated in the epithelial cells of different segments of the tubule." (PMID 39567834, 2025). "Belumosudil treatment (1 and 10 μM, 12 days) was associated with a significant decrease in cyst area in the patient-derived PKD1 cystic line (OX161/c1)." (PMID 40253509, 2025). "Delayed senicapoc treatment of already cystic Pkd1–/– metanephroi caused rapid cyst regression and restoration of a nearly normal tubular morphology in metanephroi." (PMID 41122971, 2025). "In ADPKD the single functional PKD1 allele undergoes somatic second hit inactivation, initiating cysts and cyst progression due to loss of polycystin-1 activity." (PMID 39747084, 2025). "Delayed cyst growth in Pkd1–/– metanephroi genetically deficient in Kcnn4 spurred in vivo studies of KCa3.1 function in mouse ADPKD models by generating Pkd1cko mice with inactivated Kcnn4 alleles." (PMID 41122971, 2025). "This study is significant, as it is the only one to date showing cyst formation in nephron organoids from a patient with PKD1 mutations." (PMID 40722835, 2025). "The association between GPCRs located on primary cilia and the polycystin proteins, PC1 and PC2, is crucial for regulating calcium signaling in primary cilia, and mutations in Pkd1 or Pkd2 disrupt this complex, promoting cyst formation and kidney dysfunction." (PMID 40801635, 2025). "Herein, we assessed the relationship between complement activation and cyst formation using both in vitro and in vivo Pkd1-deficient murine systems." (PMID 38912583, 2024). "Initiation of cyst formation in ADPKD is attributed to functional inactivation of polycystin-1 or -2 due to a PKD1 or PKD2 mutation." (PMID 38474184, 2024). "We tested the causal relationship between complement activation and cyst growth using a Pkd1KO renal tubular cell line and newly generated conditional Pkd1–/–C3–/– mice." (PMID 38912583, 2024). "The tubular cells of nephron-like kidney organoids derived from hPSCs carrying biallelic loss-of-function mutations in PKD1 or PKD2 display cyst formation." (PMID 37146581, 2023). "Sirt1, a member of the Sirtuin pathway, has been implicated in ADPKD, as double knockouts of Sirt1 and Pkd1 resulted in prevention of cyst formation." (PMID 37256068, 2023).
cyst (continued). "ADPKD models with PKD1 variants leading to severe cyst formation have been generated first in minipigs (OMIA 000807-9823) and more recently in cynomolgus macaques (OMIA 000807-9541)." (PMID 37372390, 2023). "In fact, heterozygous PKD1 monkeys show few renal cysts perinatally, and many live monkeys with PKD1 mutations present only mild cyst formation." (PMID 34980882, 2022). "This suggests that the mutation in PKD1 gene is likely to be responsible for the development of cysts and the underlying physiological differences exist in the mechanisms of cyst formation between different PKD1 mutations." (PMID 35629189, 2022). "We showed that suramin significantly reduced cyst growth and suppressed renal macrophage infiltration in Pkd1-deficient mice." (PMID 35955634, 2022). "HDAC6 is upregulated in Pkd1 mutant mouse cells and was found to activate factors associated with cyst growth, such as EGFR." (PMID 35847973, 2022). "This concurs with their findings that miR-182-5p suppressed WASF2, DOCK1, and ITGA4 only in PKD1-deficient mice, causing defects in the actin cytoskeleton organization, thus promoting cyst enlargement." (PMID 35205236, 2022). "PKD1 deficient pigs were previously generated to simulate the progression of cyst formation in ADPKD patients." (PMID 36309681, 2022). "Genetic deficiency of YAP and its transcriptional coactivator, TAZ, reduced Myc expression and suppressed cyst formation in Pkd1-deficient mouse kidneys." (PMID 36523654, 2022). "The suppression of cyst growth by the loss of cilia was found to occur in all segments of the renal tubules following both early and late Pkd1 or Pkd2 gene deletion." (PMID 35832738, 2022). "Because pools of cellular PC1 and PC2 interact at the cilium, primary cilia dysfunction has been linked to cyst formation in human and murine PKD1 or PKD2-dependent ADPKD." (PMID 33920158, 2021). "The presence of accumulating somatic PKD1 or PKD2 mutations can explain the initiation of cyst growth over time, and several studies have identified somatic “second hit” mutations in isolated cysts." (PMID 34948126, 2021). "Celastrol was identified as a potent inhibitor of cyst growth in both in vitro 3D cell model and a Pkd1-deficient mouse model." (PMID 33986666, 2021). "HDAC6 is upregulated in mutant mouse Pkd1 cells and activates a number of different factors associated with cyst growth, such as EGFR and EGF-induced β-catenin nuclear localisation." (PMID 34948126, 2021). "As MDCK cells do not have mutations in PKD-causative genes, we further evaluated the effect of ATM inhibition in a human ADPKD cyst model using WT 9-12 cells, which possess a homozygous PKD1 variant." (PMID 33802342, 2021). "Anti-miR-17 treatment slowed cyst growth in Pkd1flox/RC:Ksp-Cre mice, a mouse model that carries a flox allele and a R3277C mutant allele of Pkd1 gene, through regulating mitochondrial metabolism, mTOR pathway, and inflammation." (PMID 33809516, 2021). "Pkd1 loss prior to P13 causes cyst accumulation within weeks, while deletion after P14 delays cysts for 5–6 months For our slow-progressing model, we delivered tamoxifen at P21-23." (PMID 34962918, 2021). "Stress stimuli and DNA damage have been found to play roles in inhibiting PKD1 gene expression, possibly causing haploinsufficiency and cyst formation." (PMID 32724471, 2020). "Recent evidence suggests that the involved proteins interact, with decreased levels of functional polycystin-1 (PC1), encoded by PKD1, as the central element for cyst development." (PMID 33097077, 2020). "Knockdown of Pkd1 (Pkd1−/−) causes spontaneous cyst growth, which is much less pronounced in control cells (Pkd1+/+)." (PMID 32859916, 2020). "In this model, somatic mutations affecting the remaining healthy PKD1 allele are proposed to precede cyst initiation." (PMID 32163234, 2020).
cyst (continued). "Although there are many types of mouse ADPKD models, including Pkd1 or Pkd2 knockout (KO), conditional KO, and induction of hypomorphic mutations, consistent cyst formation requires biallelic mutations in most models." (PMID 31822676, 2019). "The other six monkeys showed mild cyst formation, indicating that the frequency of cyst formation tended to correlate with the mutation rate of the PKD1 gene." (PMID 31822676, 2019). "Genetic inhibition of HDAC5, even heterozygosity, can suppress cyst formation caused by the Pkd1 mutation, providing the genetic basis supporting HDAC5 as a therapeutic target for ADPKD disease intervention." (PMID 31059522, 2019). "Similar to the in vivo data, the mtDNA copy number in cyst-derived cells harboring the homozygous PKD1 mutation was significantly lower than that observed in normal cells." (PMID 28993480, 2017). "Loss-of-function mutations in either PKD1 or PKD2 or reduced levels of functional protein are causative for cyst formation, but the mechanisms behind this process are still poorly understood." (PMID 28644734, 2017). "In this study, we investigated miRNA profiles associated with severity of cyst development in the ADPKD models of Pkd1 or Pkd2 conditional knockout mice." (PMID 29074972, 2017). "Enhanced PKA activity and mitochondrial oxygen consumption in the cyst-derived cells with PKD1 heteroplasmic mutation." (PMID 28993480, 2017). "To evaluate the pathophysiological role of mitochondrial abnormalities in cyst-derived cells with a heterozygous PKD1 mutation, we treated WT 9-7 with MitoQ and evaluated superoxide levels." (PMID 28993480, 2017). "Mitochondrial abnormalities in human cyst epithelial cells derived from an ADPKD patient with a PKD1 heterozygous mutation." (PMID 28993480, 2017). "Mitochondrial abnormalities in human cyst epithelial cells derived from an ADPKD patient with a PKD1 homozygous mutation." (PMID 28993480, 2017). "To determine if liver cyst formation is sensitive to the timing of Pkd1 loss, we analyzed cyst formation following Pkd1 deletion using 250 mg/kg tamoxifen on P5, P8, and P10." (PMID 27356569, 2016). "JQ1 treatment can also delay cyst growth and kidney enlargement and preserve renal function in early stage genetic mouse strains with PKD1 mutations and ameliorates renal inflammation." (PMID 27732564, 2016). "AC6 is likely a ADPKD-relevant target as it contributes to cyst formation in Pkd1-deficient mouse kidneys." (PMID 25888842, 2015). "Functional loss of the gene products of PKD1 and PKD2, polycystin 1 and polycystin 2, leads to abnormalities in a variety of intracellular signaling pathways, which contribute to cyst initiation and expansion." (PMID 26110849, 2015). "In this study, we show that erlotinib is well tolerated and effective in controlling cyst growth in the context of loss of Pkd1, and that erlotinib can delay the growth of cysts that alisertib promotes." (PMID 26528438, 2015). "It has therefore been postulated that a heterozygote germ-line mutation in Pkd1 or Pkd2, combined with postnatal disruption of the second normal allele is required for cyst formation (the two-hit mechanism of the Knudson theory)." (PMID 23966953, 2013). "The non-lethality of Col1a1(3.6)-Cre;Pkd1flox/flox mice establishes a new model to study abnormalities in bone development and cyst formation in pancreas and kidney caused by Pkd1 gene inactivation." (PMID 23029375, 2012). "In contrast mutations in Pkd1 and Pkd2 do result in cyst formation despite normal oriented cell division, suggesting that loss of PCP-related oriented cell division is not sufficient to generate kidney cysts." (PMID 23351924, 2012). "This led to the formation of the “two-hit” hypothesis, which states that cyst initiation occurs when the normal allele of either PKD1 or PKD2 undergoes a mutation, as those tubular epithelial cells become dysfunctional and gain a growth advantage." (PMID 40722835, 2025).